IL33 (interleukin 33)
Diseases named in the same sentence as IL33 in open-access papers (continued):
Sharing a sentence is not in itself a finding about the gene and the disease.
cancer (continued). "To determine whether IL-33-activated Tregs contributed to cancer development in HBV+DEN-treated mice, we subjected Foxp3Cre, ST2 flox/flox (TregST2CKO) mice in which ST2 was specifically deleted in Tregs to HBV+DEN liver carcinogenesis protocol." (PMID 40579434, 2025). "However, given the complexity of the TME, IL-33 appears to play a controversial role during cancer progression in a context-dependent manner." (PMID 40216748, 2025). "IL-33 has been shown to promote the accumulation and suppressive capacity of regulatory T cells (Treg), contributing to immune tolerance and tissue repair, as well as facilitating immune evasion in cancer." (PMID 41284319, 2025). "SUMOylated IL-33 in the nucleus stabilizes IRF1 in HCC to promote cancer cell immune escape." (PMID 40040703, 2025). "Notably, IRF3 functions as a transcription factor regulating IL-33 expression in cancer-prone chronic inflammation, making it a potential target to inhibit chronic inflammation and cancer development." (PMID 40647388, 2025). "In addition to its role in allergy and asthma and its involvement in the development of various chronic inflammatory diseases, IL-33 plays a crucial role in the progression of chronic inflammation to cancer." (PMID 40647388, 2025). "Evaluating anti-IL-33 antibodies for their anti-cancer effects is worth considering." (PMID 39925809, 2025). "Furthermore, co-incubation of human BRCA cells with CD8+ T cells demonstrated that activated T cells were more effective at eliminating cancer cells in the presence of overexpressed IL33." (PMID 39911848, 2025). "This TIC-driven IL-33-TGF-β feedforward loop exhibited potential in cancer treatment." (PMID 39925809, 2025). "IL-33 is an epithelial-derived alarmin with various roles in cancer." (PMID 40317004, 2025). "However, the actual source of IL-33 during cancer therapy and how IL-33 contributes to a resistant TME remain incompletely understood." (PMID 40216748, 2025). "One aspect of the multiple differences in the role of IL-33 in some cancers may be related to differences in the ability of malignant cells to experience specific types of cell death." (PMID 39925809, 2025). "Furthermore, in a mouse model deficient in the NFE2L3 transcription factor, mast cell activity can be regulated through the upregulation of RAB27A, which enhances IL-33 activity and mediates the transition between inflammation and cancer." (PMID 39814702, 2025). "The expression of IL-33/ST2 in cancer tissues correlates with tumor growth and progression." (PMID 41333471, 2025). "However, a limited understanding of the relationship between basophils, cancer, and IL-33 regulation remains." (PMID 40236667, 2024). "Direct IL-33 injection into cancer patients, generation of human immunogenic cDC1s from CD34+ hematopoietic progenitor cells using IL-33-derived factors, and development of highly immunogenic human Mo-DCs using IL-33-induced factors from human PBMCs are proposed strategies." (PMID 38825642, 2024). "Understanding the diverse effects of IL-33 on immune responses in the cancer context is crucial." (PMID 40236667, 2024). "Hence, IL-33 emerges as a compelling target for cancer immunotherapy, awaiting refined therapeutic strategies to fully harness its considerable potential." (PMID 38881897, 2024). "Interleukin-33 (IL-33) is a master initiator of cancer-prone chronic inflammation." (PMID 38816352, 2024). "The IL-33/ST2L pathway, associated with type 2 immunity via ST2L+ regulatory T cells (Tregs) activation, leads to increased Treg accumulation in the TME, promoting poor prognosis in various cancers." (PMID 38778059, 2024). "IL17A influenced the level of IL33 in the cancer group (p = 0.007)." (PMID 38398137, 2024). "IL-33 exhibits pleiotropic functions in inflammatory diseases and particularly in cancer." (PMID 38662248, 2024). "In our research, we first explored the expression patterns of IL33 in a pan‐cancer context." (PMID 38923705, 2024).
cancer (continued). "While some studies indicate that IL-33 improves T cell activation and DC-mediated antigen presentation, others argue that IL-33 may lead DCs to acquire tolerogenic characteristics, inhibiting the immune system’s ability to combat cancer." (PMID 40236667, 2024). "The IL-33/ST2 signaling pathway influences tumorigenesis in various cancers." (PMID 38778059, 2024). "The crucial role of IL-33 in promoting Treg cell expansion highlights its potential as a target for therapeutic intervention in cancer immunotherapy, emphasizing the importance of understanding and utilizing IL-33 in cancer treatment." (PMID 40236667, 2024). "Thus, blocking IL-33 expression instead of its cytokine function alone is essential to achieve cancer prevention in chronic inflammation." (PMID 38816352, 2024). "Furthermore, IL-33 activates the intrinsic signaling pathway in Treg cells, which is necessary for their immunosuppressive action in cancer." (PMID 40236667, 2024). "Given the diverse involvement of IL-33, its roles in cancer remain controversial." (PMID 38825642, 2024). "However, these dual effects of IL-33 in cancer imply that IL-33-based cancer immunotherapies should be considered with caution." (PMID 38238529, 2024). "However, in cancer immunity IL-33 can display both pro- and anti-tumoural functions, depending on the specific microenvironment." (PMID 38662248, 2024). "After exposure to multiple inflammatory microenvironmental factors, molecules such as IL-4, IL-6, IL-8, IL-17α, IL-22, IL-23, IL-33, and interferon-γ, induce complex genetic/molecular changes in precancerous stem cells (pCSC) to gradually form cancer stem cells (CSCs)." (PMID 39073546, 2024). "Importantly, the cancer cell viability was significantly reduced by combination treatment consisting of α-IL-33 or α-ST2L and cisplatin." (PMID 38778059, 2024). "IL33 exhibited differential expression across various cancer types." (PMID 38923705, 2024). "Because IL-33 is expressed in epithelial cells of the skin and pancreas during chronic inflammation, statin’s efficacy in cancer suppression may be related to its ability to block nuclear and cytokine functions of IL-33 in cancer-initiating epithelial cells." (PMID 38816352, 2024). "Interleukin 33 (IL-33) is a critical initiator of cancer-prone chronic inflammation; however, its induction mechanism by environmental causes of chronic inflammation is unknown." (PMID 38816352, 2024). "IL-33 and its receptor ST2 are found to co-localize in poorly differentiated human gastric cells; functionally, IL-33 self-stimulation promotes the survival and proliferation of cancer stem cells, supposedly in cooperation with the Wnt-axis, and confers resistance to chemotherapy." (PMID 38339273, 2024). "This study significantly advances our understanding of IL33 in cancer biology." (PMID 38923705, 2024). "In addition, accumulating evidence has demonstrated that IL-33 also promotes migration of normal cells as well as cancer cells." (PMID 37629196, 2023). "Interleukin-33 (IL-33) has emerged as a critical cytokine in the regulation of the immune system, showing a pivotal role in the pathogenesis of various diseases including cancer." (PMID 37762328, 2023). "Future studies could investigate how different levels of IL-5 and IL-33 contribute to eosinophil plasticity in cancer." (PMID 37587450, 2023). "Interleukin 33 (IL-33) is a critical initiator of cancer-prone chronic inflammation; however, its induction mechanism by the environmental causes of chronic inflammation is unknown." (PMID 36711701, 2023). "All these data suggest that IL-33 may be a promising adjuvant to generate effective T cell-mediated protective immunity against cancer, with potential applications in CRC treatment through the improved efficacy of 5-FU-based therapies." (PMID 37056569, 2023).
cancer (continued). "However, interestingly, knockdown of P2X7 significantly suppressed the cancer stem transformation and IL-33 release induced by SAA, suggesting the connection between SAA and P2X7." (PMID 37925492, 2023). "PD-1-driven regulation of IL-9 production by ILC2s may be relevant in cancer as PD-1+ ILC2s were detected in human cancer, and PD-1 blockade in combination with IL-33 enhanced the anti-tumor function of ILC2s." (PMID 37189417, 2023). "The presence of different subsets of ILC2 cells in IL-33-expressing and IL-25-expressing cancers could explain the discrepancies in their observed functions." (PMID 37781372, 2023). "However, IL-33 is a dual-function cytokine, and the expression data in different cancer types are inconsistent." (PMID 37507682, 2023). "Recent studies have used IL-33 as a cancer immunotherapeutic to bolster type 1 immune responses." (PMID 37611111, 2023). "The basis for these therapies is that IL-33 is markedly down-regulated in high-grade cancers, which might serve as a mechanism to evade antitumor immunity." (PMID 37611111, 2023). "The results showed that IL-33 was a poor predictor in cancer patients." (PMID 37507682, 2023). "IL-33 can expand myeloid-derived suppressor cells (MDSCs) during cancer progression." (PMID 36291105, 2022). "Higher expression of DLL3 or IL-33 could lead to a lower survival rate based on University of California, Santa Cruz Xena Functional Genomics Explorer and The Cancer Genome Atlas data set." (PMID 35382168, 2022). "Il33 is related to cancer development, metastasis, and drug resistance." (PMID 35841025, 2022). "Previous studies have demonstrated the implication of the IL-33/STL2 pathway in cancer." (PMID 35409061, 2022). "Concluding, IL‐33 has an emergent significant role in cancer." (PMID 35344301, 2022). "IL-33 was also reported as a key driver of treatment resistance in PCa, which could be a possible target for upregulating sensitivity to cancer treatment." (PMID 36237303, 2022). "Alternatively, treatments targeting the immune components, such as MBL and IL-33 that control fungal infections could also provide a promising way to fight this deadly cancer." (PMID 35910636, 2022). "While high levels of IL-33 have been reported in sera and tissues of GC patients compared to normal controls, there is little information on comparative IL-33 expression in pre-cancer to GC development." (PMID 35677533, 2022). "Moreover, IL-33, a member of the IL-1 family, was reported to be involved in immune surveillance, and its absence can lead to immune evasion through “Cancer Immunoediting”." (PMID 36237303, 2022). "Recent findings have revealed an important contribution of IL‐33 to several cancers, where it may exert pro and less frequently anti‐tumourigenic functions." (PMID 35344301, 2022). "Targeting the IL‐33 pathway represents a potential for cancer therapy." (PMID 35344301, 2022). "Thus, the roles of innate epithelium-derived cytokines IL-25 and IL-33, and ILC2s in cancer cannot be generalized." (PMID 35658010, 2022). "Our study suggests that TNF-α directly regulates the expression of IL-33 in carcinoma cells, thus supporting the conclusion that TNF-α plays a role in immune suppression in PDA that can be overcome through blockade of bone marrow–derived macrophages in concert with immune therapy." (PMID 36256464, 2022). "Since the major increase in IL-33 in the Gem+ICB+CCR2i group was observed from carcinoma cells, we sought to test whether TNF-α can directly regulate IL-33 expression in carcinoma cells." (PMID 36256464, 2022). "However, in the triple therapy group we again observed expression in both compartments, but a profound increase in IL-33 expression in carcinoma cells." (PMID 36256464, 2022). "One previous study has reported that the activation of ST2 by IL-33 could activate CD40L signaling in a cancer mice model." (PMID 35062695, 2021).
cancer (continued). "Notably, the intervention of the IL-33/ST2 axis for cancer therapy should be approached with caution, given IL-33 is a pleiotropic cytokine with the nature of a double-edged sword, namely pro- and anti-tumorigenic functions." (PMID 34209038, 2021). "To understand the molecular level of the crosstalk between the cancers and CAFs involving IL-33, we confirmed the autocrine and paracrine effects of IL-33 on the expression of CSC properties, including chemoresistance, radioresistance, alterations in drug resistance genes, and antiapoptosis." (PMID 34298657, 2021). "To determine whether the effectiveness of cetuximab against cancer is dependent on IL‐33 and OPN targeting of NK cells, we treated nude mice that had HT‐29 cell xenograft tumors with cetuximab in vivo." (PMID 34664425, 2021). "Although the role of IL-33 in regulating basophils in anti-cancer immunity is poorly characterized, these findings may widen the scope of effector immune cells in TME activated by IL-33." (PMID 34209038, 2021). "A recent study proposed that the IL33-TGF beta niche signaling promoted cancer progression." (PMID 34298657, 2021). "Furthermore, in the environment of a human IL-33-enriched cancer type, such as CRC, ILC2s show PPARγ-dependent pro-tumoral functions." (PMID 33953160, 2021). "Others found that the IL-33/ST2 axis increases the growth of cancer cells via the MAPK/ERK/JNK signaling pathway and may serve as a prognostic indicator of patients with EOC." (PMID 34594380, 2021). "It has been hypothesized that IL-33 has a protumorigenic function in cancer cell lines, inducing an increase in invasion, migration, and chemoresistance." (PMID 34071419, 2021). "The results of this concluded that cancer did not influence the lack of renoprotection, elicited by IL-33 deficiency." (PMID 33805488, 2021). "Besides well-established IL-33/ST2 and SDF1/CXCR4 (stromal-derived factor 1/C-X-C motif chemokine receptor 4) signaling, the CAF-induced IL-33 upregulated CXCR4 via cancer cell induction of IL-33 self-production." (PMID 34298657, 2021). "Increased IL-33 expression is closely related to the growth and metastasis of cancer cells." (PMID 34026612, 2021). "Targeting the interleukin-33/CXCR4 signaling circuit attenuated cancer aggressiveness and may have potential as a treatment strategy for improving the prognosis of HNSCC patients." (PMID 34298657, 2021). "This is due to the dichotomous actions of IL33 and MCs in cancer." (PMID 32719677, 2020). "Considering the dual role of IL-33 in cancer, it might be considered carefully in drug development as a target." (PMID 33308251, 2020). "Understanding the mechanisms by which IL-33 targets PD-1 in various cancer types may help improving immunotherapy protocols." (PMID 33329534, 2020). "Considering that IL-33 could play a dual role in cancer, it might be considered carefully in drug development as a target." (PMID 33308251, 2020). "Although the role of basophils in cancer immunity is still unclear, this latter observation may broaden the spectrum of immune effector cells that can be activated by IL-33 within the TME." (PMID 33329534, 2020). "Furthermore, we attempt a broader discussion of the emerging functions of IL‐33 in host defence, tissue repair, metabolism, inflammatory disease and cancer, suggesting potential avenues to manoeuvre IL‐33/ST2 signalling as treatment options." (PMID 32566227, 2020). "This evidence supports the roles of IL-33 in both promoting and suppressing cancer." (PMID 33046978, 2020). "Moreover, previous studies have reported that IL-33/ST2 in human cancers is expressed in a variety of cells, including epithelial cells, stromal cells, infiltrating lymphocytes and Tregs, and microvessels." (PMID 32246094, 2020). "Notably, TNFAIP8L3, CCL14, CX3CR1, CCL21, IL1R1, and IL33 had higher expression levels in the lower-TMB subtype of at least 13 cancer types, while had higher expression levels in the higher-TMB subtype of at most 2 cancer types." (PMID 30634925, 2019).
cancer (continued). "IL-33 detected by immunogenic techniques in serum is used as a prognostic biomarker for chronic heart failure and multiple sclerosis, but has recently also been proposed as a prognostic marker for cancer diseases." (PMID 31396219, 2019). "Recent studies have demonstrated that IL-33 has a close relationship with many kinds of human malignant tumours, in which it may provide pro-tumourigenic functions." (PMID 31889095, 2019). "The role of IL-33 in cancer immunity however remains controversial." (PMID 31396219, 2019). "The same infective agents could enhance lipogenesis, inducing the expression of cancer stem cell genes with a TLR4/IL-33-mediated pathway." (PMID 31130612, 2019). "Although the role of IL-33 in tumorigenesis and cancer immunity thus remains controversial, further studies should help to elucidate whether IL-33/ST2 signaling in mast cells can contribute to human or experimental tumorigenesis." (PMID 31500217, 2019). "Moreover, exogenous administration of IL-33 to wild type breast tumor-bearing animals reduced NK cytotoxicity and increased cancer progression." (PMID 31652497, 2019). "Our analyses further suggest that neutrophil numbers and IL33 levels could be potential factors affecting the survival of mutant-CASP8 carcinomas." (PMID 30775178, 2019). "Interleukin-33 (IL-33) participates in various types of diseases including cancers." (PMID 30119635, 2018). "The role of basophils in anti-cancer immunity is poorly characterized and the effects of IL-33 in stimulating or regulating basophils responses in cancer are unknown." (PMID 30483263, 2018). "IL-33 induces cancer cell invasion and confers chemotherapy resistance in vitro." (PMID 30483263, 2018). "The function of IL-33/ST2 axis in cancer cells is poorly understood." (PMID 30119635, 2018). "IL-33 knockdown decreased the enhanced cancer glycolysis, lipogenesis and stemness by gram-negative bacteria, suggesting IL-33 as an effective regulator of cancer metabolism and cancer stem cell properties." (PMID 29568370, 2018). "Moreover, IL-33 was shown to play an important role in several cancers due to its pro and anti-tumorigenic functions." (PMID 30416507, 2018). "Furthermore, the presence of IL-33 in the microenvironment augments the anti-cancer function of ILC2s." (PMID 29440650, 2018). "The precise role of IL-33 in pancreatic inflammation and cancer remains to be elucidated." (PMID 30205617, 2018). "IL-33/ST2 signaling is emerging as important pathway in cancer biology." (PMID 30205617, 2018). "Similarly, high level of serum IL-33 also indicated a poor prognosis in patients with these two types of cancers." (PMID 30619376, 2018). "Recent studies identified IL-33 as a critical factor involved in cancer pathogenies." (PMID 29568370, 2018). "To date, all studies except of one have linked increased serum levels of IL-33 and sST2 in cancer patients to negative prognosis." (PMID 30426271, 2018). "The topic concerning IL-33 initiated cancer cell death is still emerging." (PMID 30619376, 2018). "Together with other recent researches of the IL-33/ST2 axis in human cancers, our work supports the hypothesis that the IL-33/ST2 axis may play an important role in ESCC progression." (PMID 30559604, 2018). "Current data strongly suggest that IL-33 is involved in the pathogenesis of cancers." (PMID 30559604, 2018). "Indeed, IL-33 is considered an “alarmin” able to activate different actors of the innate immune system, mediating a variety of immune reactions including anti-cancer immune responses." (PMID 30483263, 2018). "The role of IL-33 in tumorigenesis and cancer immunity remains controversial." (PMID 30483263, 2018). "However, there are no published studies mentioning a direct relationship between TH17 cells and IL-33 in cancers." (PMID 30416507, 2018). "IL-33 was identified as a pro-cancer cytokine and fueled the glycolysis of NSCLC cells." (PMID 29568370, 2018).